RARB (retinoic acid receptor beta)
Diseases named in the same sentence as RARB in open-access papers (continued):
Sharing a sentence is not in itself a finding about the gene and the disease.
oral cancer (7 papers, 2006 to 2023). "The modulation of RARβ expression by this mean appears to be an initial, reversible effect in oral cancer development, as tissues from later in the process show loss of expression by non-reversible means, such as chromosome 3p deletion." (PMID 34439217, 2021). "The explanation for the repression of RARβ expression in D19, D20, and D34 was promoter hypermethylation, emphasising epigenetic mechanisms in oral cancer pathogenesis, and the importance of the combination of drugs for chemoprevention." (PMID 34439217, 2021). "In the future, we should consider retinoid acid use or RARB related drugs for areca users who are found to have oral tumors or oral cancer to reduce the incidence of oral cancer and to provide a better treatment outcome." (PMID 25197641, 2014). "In the present study, we investigated the role of RARB hypermethylation of CpG islands in OSCC mouse model and its association with RARB expression in human oral cancer cell lines." (PMID 25197641, 2014). "We found that a combination of six genes (TP73, CASP8, RARB, KLLN, GSTP1, and CHFR) could distinguish oral cancer from clinically diagnosed OPMDs with high diagnostic performance (area under the curve [AUC], 0.885; sensitivity, 77.8%; and specificity, 87.1%)." (PMID 35681626, 2022). "Therefore, betel quid related hypermethylation of RARB will really increase the tumorigenesis and poor treatment outcome of oral cancer." (PMID 25197641, 2014). "Changing in RARB expression isassociated with cellular sensitivity to retinoid in numerous cancer cells, includingHNSCC cells, betel quid related hypermethylation of RARB will increase the tumorigenesisand poor treatment outcome of oral cancer (Laiet al., 2014)." (PMID 37338302, 2023). "In addition, we examined whether the repression of RARB transcription could be reversed by 5-aza-dC in human oral cancer cell lines, and finally, we evaluated the three main DNA methyltransferases that were involved in RARB hypermethylation." (PMID 25197641, 2014). "Evaluation of the combination of six genes with aberrant methylation (RARB, KLLN, CHFR, TP73, GSTP1, and CASP8) was particularly useful for identifying early-stage oral cancer in clinically diagnosed patients with OPMDs with high diagnostic performance." (PMID 35681626, 2022). "The RARB gene was a candidate target to verify the methylation status in these mouse OSCC tongues tissues and in human oral cancer cell lines that were also treated by 5′-aza-2′-deoxycytidine (5-aza-dC)." (PMID 25197641, 2014). "Interestingly, RARB was hypermethylated in mouse OSCC and reexpression by 5-aza-dC treatment in human oral cancer cell lines." (PMID 25197641, 2014).
squamous cell carcinoma (7 papers, 2004 to 2021). A carcinoma arising from squamous epithelial cells. "RARβ hypermethylation was significantly higher in adenocarcinoma (AC) compared to squamous cell carcinoma (SCC), pooled OR is 0.68 (95% CI = 0.52-0.89, p = 0.005)." (PMID 28008143, 2017). "Two of the squamous cell carcinomas showed the same methylation pattern for RARB, and one for RASSF1A." (PMID 18702824, 2008). "The co-methylation of SIX6, RARB and SOX1 occurred less frequently in adenocarcinoma (ADC) than in squamous cell carcinoma (OR, 0.45; 95% CI, 0.25–0.76)." (PMID 23599765, 2013).
depression (6 papers, 2014 to 2025). "Murine RARB knock-out models reveal its intrinsic link to cognitive function, as both long-term potentiation and depression, which underlie hippocampal plasticity, are functionally ablated." (PMID 30532020, 2020). "RARB levels were shown to be lower in the platelet protein profile in patients with major depression than in healthy controls." (PMID 40806189, 2025). "The most interesting finding in this study was higher PDIA3 expression and lower FGB, GPX-1, and RARB expression in patients with major depression than in healthy controls." (PMID 24383611, 2014). "To further determine the causal relationship between plastic changes of cingulate RARB and neuropathic pain, we overexpressed RARB in the ACC and found that supplementation of RARB significantly alleviated pain hypersensitivity and related anxiety and depression in SNI-treated mice." (PMID 40591414, 2025). "We next observed whether RARB in the ACC relieves neuropathic pain–related anxiety and depression." (PMID 40591414, 2025). "No significant changes in RARB expression were observed in the ACC after chronic CORT or CRS exposure, suggesting specific involvement of ACC RARB in the development of chronic pain and associated depression but not in non–pain-related depression." (PMID 40591414, 2025). "In contrast, RARB in the ACC may not be involved in depression with no pain, since we found no significant alteration of cingulate RARB in rodent models of chronic CORT and CRS exposure." (PMID 40591414, 2025). "The levels of fibrinogen beta chain (FIBB), fibrinogen gamma chain (FIBG), retinoic acid receptor beta (RARB), glutathione peroxidase 1 (GPX1), SH3 domain-containing protein 19 (SH319), and T-complex protein 1 subunit beta (TCPB) were lower in patients with major depression than in healthy controls." (PMID 24383611, 2014). "Finally, we determined whether RARB in ACC is involved in depression without chronic pain." (PMID 40591414, 2025).
pancreatic cancer (6 papers, 2002 to 2025). "Activation of RARβ transcriptionally leads to decreased expression of the protein myosin light chain 2 in pancreatic cancer cells." (PMID 39850424, 2025).
prostate tumor (6 papers, 2011 to 2025). "RARB silencing is associated with resistance to retinoic acid in epithelial carcinogenesis and in breast and prostate tumours." (PMID 36147741, 2022). "It is proposed that RARβ silencing by promoter methylation is a crucial event in prostate tumor progression and that epigenetic changes in the TIG1 promoter, and possibly in the promoters of other retinoid response genes, are downstream events to RARβ deficiency." (PMID 22191037, 2011). "Of the genes reported to be frequently differentially methylated between African American and European American prostate tumours (e.g., RARB, TIMP3), none were significantly differentially methylated in our cohort." (PMID 41057544, 2025). "Numerous studies investigating GSTP1, RARB and RASSF1 DNA promoter methylation have reported that hypermethylation in prostate tumour tissue may represent a biomarker of early cancer diagnosis, in accordance with our results." (PMID 27576364, 2016).
acute myeloid leukemia (5 papers, 2007 to 2021). Acute myeloid leukemia (AML) is a group of neoplasms arising from precursor cells committed to the myeloid cell-line differentiation. "Combination of the two FDA approved drugs -RA for acute myeloid leukaemia and rapamycin for TSC mutation- normalised ALDH and ADH expression and activity, restored RARβ expression and reduced cellular proliferation and migration." (PMID 34178631, 2021). "RA for example is an FDA approved drug for acute myeloid leukaemia as RA can normalize RARβ levels and limit cancer cell migration and consequent disease progression." (PMID 34178631, 2021). "It was known that the promoter of the RARβ gene is frequently hypermethylated in acute myeloid leukemia and cholangiocarcinoma." (PMID 18166136, 2007). "RUNX1/ETO, which causes acute myeloid leukemia (AML), acts as a dominant-negative repressor of RUNX1 target genes, including colony-stimulating factor 1 receptor (CSF1R/c-fms), GM-CSF, tumor suppressor p14(ARF) and the retinoic acid receptor β (RARB)." (PMID 23860209, 2013).
atherosclerosis (5 papers, 2021 to 2025). A disease characterized by the build-up of fatty material and calcium deposition in the arterial wall resulting in partial or complete occlusion of the arterial lumen. "Recent studies have shown that a genetic variant of the RARB gene (rs116199914) contributed to the development of subclinical atherosclerosis in patients with RA." (PMID 37008317, 2023). "For example, it has been reported that retinoic acid (RA) reduces plaque formation in an atherosclerosis prone mouse model, and here, we observed an upregulation of RA receptors (RARB) and two RA receptor responsive genes (DHRS3 and RARRES1) following abrogation of AMPA receptor signaling." (PMID 33959644, 2021).
coloboma (5 papers, 2020 to 2024). An abnormality in which a part of a structure in one or both eyes is missing. "Indeed, morpholino knockdown of rarga caused dose‐dependent ocular coloboma; a comparatively mild and partial rescue of the phenotype was observed only with coinjection of human wild‐type RARB mRNA." (PMID 31816153, 2020). "Upon coinjection of rarga SB morpholino with RARB wild‐type mRNA, 39% of embryos displayed coloboma compared with 65% of embryos injected with morpholino alone." (PMID 31816153, 2020). "We identified novel variants in genes such as TFAP2A and CHD7, and previously reported variants in RARB and BMP7, indicating that mutations in known coloboma‐associated genes account for only 4.5% of the coloboma cohort analyzed." (PMID 31816153, 2020). "Of the 38 known coloboma‐associated genes, the analysis identified novel variants in two genes, CHD7, TFAP2A, and previously reported variants in RARB and BMP7, in a total of four unrelated families." (PMID 31816153, 2020). "Thus, knockdown of the zebrafish equivalent to RARB gene, rarga, results in a phenotype reminiscent of human coloboma." (PMID 31816153, 2020). "The results were consistently replicated during multiple injections and the direction of change in the proportion of embryos with coloboma suggests an effect of RARB wild‐type mRNA but not of RARB‐mutant mRNA." (PMID 31816153, 2020).
cognitive deficit (4 papers, 2020 to 2026). "We expand this here by demonstrating the rare variation in RARB is associated with marked cognitive impairment (CD subtype) in schizophrenia." (PMID 30532020, 2020). "RARB rare variant burden was also associated with reduced cerebellar volume in the cases with marked cognitive deficit, and with covariation in grey matter throughout the brain." (PMID 30532020, 2020). "On the other hand, several reports indicate that both acute and chronic alcohol elevate RA in adult and fetal brain and in the developing or adult cerebellum, and an antagonist of RARβ suppresses RARβ expression and reverses chronic ethanol-induced cognitive impairment." (PMID 37205047, 2023). "Cases with severe cognitive deficits, while not further differentiated by PRSRet, were enriched with rare variation in the retinoic acid receptor beta gene RARB, detected through whole-genome sequencing." (PMID 30532020, 2020).
esophageal cancer (4 papers, 2013 to 2023). A primary or metastatic malignant neoplasm involving the esophagus. "In a study on esophageal cancer cells, BPDE was found to suppress Rarβ expression via promoter hypermethylation by recruiting DNMT3A." (PMID 23596512, 2013).
esophageal squamous cell carcinoma (4 papers, 2007 to 2022). Esophageal squamous cell carcinoma (ESCC) is a type of esophageal carcinoma (EC) that can affect any part of the esophagus, but is usually located in the upper or middle third. "This study showed that smoking status and low RARβ expression were associated with DNMT1 overexpression in esophageal SCC patients." (PMID 36142861, 2022).
lung adenocarcinoma (4 papers, 2009 to 2022). A carcinoma that arises from the lung and is characterized by the presence of malignant glandular epithelial cells. "In the paper of Wan and colleagues the defect in the inhibition of AP-1 by RARβ was investigated in the H1792 lung adenocarcinoma cells, resistant to the ATRA growth-inhibitory effect, despite the abundant levels of RARβ." (PMID 32012980, 2020). "The authors showed that despite the lung adenocarcinoma H1792 cell line express abundant mRNA levels of RARβ, it was resistant to the growth-inhibitory effects of ATRA, suggesting probably defect in retinoid signaling." (PMID 32012980, 2020). "Further, both shRNA and siRNA knockdown of RIP140 enhanced RA induction of RARB but not RARA in the RA-responsive murine lung adenocarcinoma line, ED-1 (data not shown)." (PMID 19862326, 2009).
ovarian carcinoma (4 papers, 2004 to 2025). A malignant neoplasm originating from the surface ovarian epithelium. "The upregulation by fenretinide of the expression of RARβ and RARβ was associated with fenretinide’s antiproliferative action in ovarian cancer cells." (PMID 28448568, 2017). "We observed that RARβ mRNA expression was low in ovarian cancer cell lines, relative to that in normal cells with our cDNA microarrays." (PMID 31615043, 2019). "The impaired mRNA levels of RARβ and RARRES1 in ovarian cancer tissues were further confirmed in the Oncomine database, suggesting that expression of retinoid-related genes is altered in human ovarian cancer cells." (PMID 31615043, 2019).
schizophrenia (4 papers, 2020 to 2023). A major psychotic disorder characterized by abnormalities in the perception or expression of reality. "However, rare variation in retinoid genes was only enriched in schizophrenia cases with severe CD, with the retinoic acid receptor beta gene RARB significantly associated with this subtype." (PMID 30532020, 2020). "As RARB is enriched with rare variants only in the CD schizophrenia subtype, we investigated whether an increased burden of rare variation in this gene might be linked to specific neuroanatomical features." (PMID 30532020, 2020). "RARB involvement in schizophrenia more broadly is supported by evidence of increased burden of common variation in this gene." (PMID 30532020, 2020). "This spatiotemporal transcription profile suggests that compromised RARB function may contribute to aberrant dopaminergic signalling, which occurs in schizophrenia, but may also impair normal cognitive development in early life." (PMID 30532020, 2020). "Some of these genes (RARB, ZMAT4) were correlated with grey matter volume differences between patients with schizophrenia and healthy control." (PMID 36833173, 2023). "This suggests subtle alteration of RARB function, independent of cognitive status, is involved in the pathophysiology of schizophrenia but with likely less magnitude than rare variation." (PMID 30532020, 2020).
triple-negative breast carcinoma (4 papers, 2020 to 2026). An invasive breast carcinoma which is negative for expression of estrogen receptor (ER), progesterone receptor (PR), and human epidermal growth factor receptor 2 (HER2). "From a basic and mechanistic standpoint, an important result of the study regards the specific involvement of the retinoid receptor RARβ in the anti-tumor action exerted by all-trans retinoic acid in sensitive triple-negative breast cancer cells." (PMID 33081033, 2020).
Anophthalmia (3 papers, 2015 to 2019). Absence of the globe or eyeball. "Mutations in the gene for RARβ also cause anophthalmia in human, but RARβ knockout alone does not cause this phenotype in mice." (PMID 26343735, 2015). "If the mouse model is the only source of information, it may be concluded that ALDH1A3 and RARβ play no role in anophthalmia and that ABCA4 plays no role in retinitis pigmentosa." (PMID 26343735, 2015).
cervical disease (3 papers, 2015 to 2025). "Using prospective time-to-event data, we detected associations between CADM1-, DAPK1-, PAX1-, and RARB-related CpGs and cervical disease progression, and we identified novel progression-associated CpGs." (PMID 37932662, 2023). "RARβ regulates cell proliferation; its promoter methylation is positively correlated with cervical disease grade." (PMID 40159638, 2025). "Moreover, RARB silencing was documented in both cervical dysplastic and carcinoma cells, supporting a role for this protein in suppressing cervical carcinogenesis." (PMID 25826459, 2015).
colitis (3 papers, 2022 to 2025). Inflammation of the colon. "Importantly, reduced Rarβ was only found in the colon, suggesting that colitis had a greater impact on RA signaling in the colon than in the ileum." (PMID 35889745, 2022). "In the brain, the colitis mice had reduced Aldh1a1 but increased Rarβ mRNA, which might suggest reduced production and perhaps a compensatory induction of the receptor." (PMID 35889745, 2022). "Intriguingly, our results enriched the involvement of RARβ in the regulation of SAA expression, suggesting that short‐term RARs‐pan‐antagonist treatment blocked RA‐induced downregulation of SAA1/2 with crosstalk to C/EBPA in colitis colonic epithelial cells." (PMID 37983567, 2023).
embryonal carcinoma (3 papers, 2009 to 2023). A non-seminomatous malignant germ cell tumor characterized by the presence of large germ cells with abundant cytoplasm resembling epithelial cells, geographic necrosis, high mitotic activity, and pseudoglandular and pseudopapillary structures formation. "The hypothesis that in vitro and in vivo pathways are comparable is supported by significant up-regulation of RARα and RARβ mRNA, but rapid down-regulation of RARγ and RXRγ mRNA during RA-induced neuronal differentiation of mouse embryonal carcinoma cells." (PMID 19642999, 2009). "Finally, it is worth mentioning that these findings performed in P19 embryonal carcinoma cells were also confirmed in mouse embryonic stem cells, confirming the potency of the synergistic action of both RARβ and RARγ agonists to lead to neuronal cell specialization." (PMID 38137880, 2023).
injury (3 papers, 2019 to 2024). Damage inflicted on the body as the direct or indirect result of an external force, with or without disruption of structural continuity. "RARβ agonists can activate the RARβ receptor which initiates axonal outgrowth in models of nerve injury and leads to functional recovery." (PMID 33069074, 2020). "Unlike the vast majority of targets explored for SCI therapy, the neuronal RARβ signalling pathway can concomitantly change various aspects of the molecular and cellular pathology that arises after nerve injury as it modulates transcriptional patterns and has additional non-transcriptional effects." (PMID 39228795, 2024).
lymph node metastasis (3 papers, 2010 to 2014). "The retinoic acid receptor β (RARβ) is not expressed in 50% of invasive breast carcinoma compared with normal tissue and it has been associated with lymph node metastasis." (PMID 24720764, 2014). "For lymph node metastasis, ten CpGs from six genes were found to be significant: CDH1 (site 10), CDH13 (sites 7 and 8), MINT3 (sites 3 and 4), CXCL12 (sites 1 and 3), RARB (site 6) and APC (sites 1 and 6)." (PMID 25052224, 2014).
oral squamous cell carcinoma (3 papers, 2014 to 2022). "Even treatments such as vitamin A and beta carotene have been reported to be effective in healing oral leukoplakia and RARβ expression inhibits oral squamous cell carcinoma bone invasion." (PMID 32684934, 2020).
thyroid tumor (3 papers, 2016 to 2017). A benign or malignant neoplasm affecting the thyroid gland. "Quantitative assessments of RARβ and its association with BRAF mutations have revealed promoter methylation of this gene in thyroid tumor genesis." (PMID 28926589, 2017). "Since thyroid carcinogenesis is accompanied by aberrances in miRNA expression and a consequent deregulation of their target genes, we analyzed the implication of this process in silencing RARB in thyroid tumors." (PMID 27011326, 2016).